FGF16 (fibroblast growth factor 16)
Diseases named in the same sentence as FGF16 in open-access papers (continued):
Sharing a sentence is not in itself a finding about the gene and the disease.
schizophrenia (1 paper, 2025). A major psychotic disorder characterized by abnormalities in the perception or expression of reality. "However, we identified 20–45 factors in ADHD, ASD, and schizophrenia, including semaphorin 3, IL-27 receptor subunit alpha, and fibroblast growth factor 16, which were considered clinically significant pro-inflammatory mediators." (PMID 40082977, 2025).
syndactyly (1 paper, 2022). A disease characterized by the presence of syndactyly, including syndromic and non-syndromic forms. "Candidate gene studies on HOXD13, LMBR1, FGF16, BHLHA9, to understand their contribution to both cutaneous and synostosis syndactyly phenotypes, could enhance screening." (PMID 35549993, 2022).
cancer (7 papers, 2019 to 2024). A tumor composed of atypical neoplastic, often pleomorphic cells that invade other tissues. "Recently, FGF16 is implicated in the progression of hepatocellular, lung, and embryonic carcinoma with unique mechanistic action for each cancer type." (PMID 37222403, 2023). "It was demonstrated that FGF16 regulate MAPK pathway in cancer cells, which is also critical for cell proliferation." (PMID 31292167, 2019). "The onset of epithelial–mesenchymal transition (EMT), a prerequisite for cancer metastasis, was observed in human mammary epithelial cell-line MCF10A by FGF16." (PMID 37222403, 2023).
tumor (7 papers, 2011 to 2023). "FGF16 (Fibroblast Growth Factor 16) is associated with embryonic development, cell growth, morphogenesis, tissue repair, tumor growth, and proper heart development." (PMID 35615375, 2022). "Fgf16 encoded a member of a family of proteins which possessed broad mitogenic and cell survival activities, and were associated with a variety of biological processes such as embryonic development, tumor growth and invasion, cell growth, morphogenesis, tissue repair." (PMID 30386697, 2018). "The size of the tumor, as induced by FGF16, was significantly bigger than that of empty vector transfected set supporting the contribution of FGF16 in the growth of primary tumor." (PMID 37222403, 2023). "Moreover, gradual growth in tumor size reinforced the oncogenic potential of FGF16." (PMID 37222403, 2023).
cardiac disease (2 papers, 2014 to 2016). "Further studies are needed to highlight pathogenic mechanisms of the FGF16 mutations, and the possible correlation between FGF16 mutations and cardiac disease needs to be explored in a larger number of patients." (PMID 25333065, 2014). "In conclusion, this study not only establishes mutations in exons 1, 2 or 3 of FGF16 as the cause of X-linked recessive MF4 but also suggests an association of FGF16 nonsense mutation with cardiac disease." (PMID 25333065, 2014). "Our findings establish that a mutation in exon 1, 2 or 3 of FGF16 results in X-linked recessive MF4 and expand the phenotypic spectrum of FGF16 mutations to include a possible correlation with heart disease." (PMID 25333065, 2014). "FGF16 has not been previously implicated in human heart disease, but it is known that embryonic heart development in mice requires Fgf16." (PMID 25333065, 2014).
FGF16 also shares sentences with these, for which no sentence is quoted: developmental delay (1 paper); diabetes (1); endometritis (1); hepatocellular carcinoma (1); hyperglycaemia (1); infection (1); melanoma (1); metabolic syndrome (1); Obesity (1).